IDO1 (indoleamine 2,3-dioxygenase 1)
Diseases named in the same sentence as IDO1 in open-access papers (continued):
Sharing a sentence is not in itself a finding about the gene and the disease.
experimental autoimmune encephalomyelitis (13 papers, 2009 to 2022). An autoimmune demyelinating disease of the central nervous system that is produced experimentally in animals by the injection of homogenized brain or spinal cord in Freund's adjuvant. "Inhibition of IDO1 with n-acetyl 5-hydroxytryptamine, a positive allosteric modulator of IDO1, can eliminate neuroinflammation in mice with experimental autoimmune encephalomyelitis (AE), a condition associated with IDO-AHR signaling." (PMID 35096208, 2022). "IDO has been reported to be immunosuppressive in different autoimmune models such as experimental autoimmune encephalomyelitis and collagen-induced arthritis, as demonstrated by using pharmacological inhibitors of IDO and by using IDO1-deficient mice." (PMID 26914138, 2016). "Similarly, IDO1-deficient mice showed exacerbation of experimental autoimmune encephalomyelitis (EAE), increased Th1 and Th17 cells, and decreased Treg cells." (PMID 33552055, 2020). "In fact, N-acetlyserotonin was recently discovered as a positive allosteric modulator of IDO-1 and abrogated neuroinflammation in an experimental autoimmune encephalomyelitis (AE) model by engaging IDO-AhR signaling." (PMID 34205235, 2021). "During experimental autoimmune encephalomyelitis (EAE), IDO1 induction was shown to downregulate neuro-inflammation." (PMID 26378585, 2015). "In experimental autoimmune encephalomyelitis (EAE), an animal model for MS, IDO1 activity is increased in the spleen during pre-clinical phases, and IDO1-positive microglia and macrophages have been detected in brain and spinal cord at symptom onset, correlating with disease severity." (PMID 33552055, 2020).
inflammatory bowel disease (13 papers, 2012 to 2024). A spectrum of small and large bowel inflammatory diseases of unknown etiology. "Indoleamine-pyrrole 2,3-dioxygenase-1 (IDO-1) expression is associated with low serum tryptophan concentrations and is increased in the gastrointestinal tract of humans with inflammatory bowel disease (IBD)." (PMID 31181125, 2019). "IDO-1 expression is high in inflammatory bowel diseases notably in IECs and has often been positively associated with the severity of gastrointestinal diseases and inflammatory-induced colon tumorigenesis, with no causal implication." (PMID 30619249, 2018). "Upregulation of IDO1 is observed during intestinal inflammatory disorders, including human inflammatory bowel diseases." (PMID 39120289, 2024). "Although the specific mechanisms of IDO1 remain obscure, numerous studies have shown an increased expression of IDO1 in inflammatory bowel disease, infection, and diverticulosis." (PMID 34306038, 2021). "Possibly, the absence of an extensive inflammatory reaction as seen in invasive cancer or inflammatory bowel disease tissue results in lower IDO1 expression levels." (PMID 22108515, 2012). "Indoleamine 2,3-dioxygenase 1 activity, which is reflected in the kynurenine:tryptophan (KT) ratio, therefore modulates systemic and local immune responses and has been used as a marker in systemic inflammatory conditions including inflammatory bowel disease and HIV." (PMID 29926747, 2018). "More importantly, these acute activation processes of PI3K-AKT signaling were critical for the production of anti-inflammation factors such as IDO1 and TSG-6 and anti-inflammatory therapeutic effect in the inflammatory bowel disease (IBD) model." (PMID 36195887, 2022).
Alzheimer disease (12 papers, 2010 to 2023). A progressive, neurodegenerative disease characterized by loss of function and death of nerve cells in several areas of the brain leading to loss of cognitive function such as memory and language. "IDO-1 inhibition also has therapeutic potential in the treatment of Alzheimer’s disease by mitigating the impact of amyloid-driven chronic CNS inflammation and the resultant generation of neurotoxic KP metabolites through the upregulated expression of IDO-1." (PMID 37371332, 2023). "It was reported that IDO1 levels are increased in the brain in the context of Alzheimer’s disease." (PMID 33679331, 2021). "IDO1 protein expression is localised to plaques and tangles in the Alzheimer's disease brain." (PMID 22254144, 2011). "Elevated expression of IDO1, which results in the promotion of the KYN pathway, has been observed in the brain in the context of Alzheimer’s disease." (PMID 33679331, 2021).
Crohn disease (12 papers, 2013 to 2026). A gastrointestinal disorder characterized by chronic inflammation involving all layers of the intestinal wall, noncaseating granulomas affecting the intestinal wall and regional lymph nodes, and transmural fibrosis. "Analysis of scRNA-seq datasets from patients with Crohn's disease with ascending colon involvement also supported increased IDO1 expression in a subpopulation of crypt surface epithelial cells." (PMID 41919496, 2026). "Increased expression of IDO1 in epithelial cells has also been reported in ilea of Crohn's disease patients." (PMID 40386941, 2025). "An analysis of colonic biopsy sections from patients with Crohn’s disease revealed a similar upregulation of IDO1, specifically in involved regions." (PMID 33396621, 2020). "Increased IDO-1 expression in the intestinal mucosa also decreases serum tryptophan concentrations and increases kynurenine concentrations in patients with Crohn’s disease a type of IBD in humans." (PMID 31181125, 2019). "The kynurenine-to-tryptophan ratio, which is an indicator of IDO-1 activation in the intestinal tract, has been shown to be negatively correlated with Crohn’s disease activity." (PMID 31181125, 2019). "All patients with IDO1 SNPs had serum sampled during a period of moderate to severe Crohn's disease activity." (PMID 25541686, 2014). "IDO1 SNPs were rare and not linked to Crohn's disease risk in this population." (PMID 25541686, 2014). "Analysis of tissue sections reveal that IDO1 is highly expressed in IFN-γ treated organoids and in involved colonic regions of patients with active Crohn’s disease." (PMID 33396621, 2020). "IDO1 expression is known to be upregulated in several intestinal diseases, including IBD, where it has been shown to be highly expressed in inflamed colonic lesions of Crohn’s disease patients." (PMID 33396621, 2020). "IDO1 SNPs were rare (1.7% non-IBD vs 1.1% CD; p = NS) and not linked to Crohn's disease diagnosis in this population." (PMID 25541686, 2014).
endometriosis (12 papers, 2016 to 2025). The growth of functional endometrial tissue in anatomic sites outside the uterine body. "In rectocervical endometriosis lesions, increased IDO1 expression is associated with increased COX-2 and MMP-9 expression, promoting enhanced adhesion and invasion of endometrial stromal cells." (PMID 41488658, 2025). "Deep infiltrative endometriosis is characterized by IDO1/COX-2/MMP-9 axis predominance driving tissue destruction and paradoxical Treg recruitment via CCL17/CCL22." (PMID 41488658, 2025). "A study showed a high kynurenine/tryptophan ratio, which is also an index for IDO1 activity, in endometriosis compared with control tissues." (PMID 33174185, 2021). "To investigate whether IDO1 participates in the differentiation of Treg cells in endometriosis in vivo, we established an endometriosis-disease mouse model." (PMID 27906184, 2016). "Moreover, estrogen promoted the expression of IDO1 in both ESCs and macrophages, which, on a side-note, explains that ectopic ESCs have high expression of IDO1 in endometriosis." (PMID 27906184, 2016). "Additionally, IDO1 may activate immunosuppressive macrophages, which can facilitate the survival of endometrial tissues and seem to be involved in the progression of endometriosis." (PMID 39120289, 2024). "Therefore, to evaluate the specificity of macrophage PD-L1 and IDO1 expression in Mtb infection, we used immunohistochemistry (IHC) to compare both proteins on a tissue microarray of granulomas from sarcoidosis (n = 9), foreign body uptake (n = 4), endometriosis (n = 4) and xanthomatosis (n = 3)." (PMID 35058616, 2022). "MeSCs from endometriosis patients show also up-regulated CD9, CD10, CD29, indoleamine 2,3-dioxygenase-1 (IDO-1), COX-2, IL10, IFN-γ and monocyte chemoattractant protein-1 (MCP-1) expression." (PMID 36612107, 2022). "Moreover, positive expression of IDO1, TDO2 and IL4I1 was related to advanced stage, metastasis, bilateral tumours, endometriosis and tumour rupture (p < 0.05) respectively." (PMID 38062922, 2023). "Another promising treatment option is based on the demonstration that the estrogen – indoleamine 2,3-dioxygenase-1 (IDO1) – mannose receptor C, type 2 (MRC2) axis participates in the differentiation and function of Tregs and is involved in development of endometriosis." (PMID 35935991, 2022). "Interestingly, in a differently designed study, IDO1 and COX2 gene expression was found to be higher in menstrual blood-derived stromal cells in women with endometriosis compared to healthy controls after culture in a transwell system with PBMCs." (PMID 29230250, 2017). "Thus, blockage of IDO1 in ectopic lesions, which does not influence the physiological functions of estrogen, may be considered a potential therapy for endometriosis." (PMID 35935991, 2022). "According to the findings above, MRC2 is downstream to IDO1, and IDO1 is involved in the differentiation of Treg in ectopic lesion, hinting the possibility that MRC2 may participate in the activity that IDO1 regulates the differentiation of Treg in endometriosis." (PMID 27906184, 2016). "Thus, blockage of IDO1 in the ectopic lesion, which does not influence physiological functions of estrogen, may be considered a potential therapy for endometriosis." (PMID 27906184, 2016).
HIV-1 infection (12 papers, 2013 to 2025). The type species of lentivirus and the etiologic agent of acquired immunodeficiency syndrome (AIDS). "Among the enzymes in this pathway, IDO1 has been recognized as a significant immune response checkpoint, playing an important role in HIV-1 infection-associated immune dysfunction, even in the context of antiretroviral therapy." (PMID 39120289, 2024). "Because of the immunosuppressive outcome due to long-term IDO1 expression, IDO1 plays a counterintuitive role during chronic HIV-1 infection." (PMID 29342871, 2018). "Specifically, the recovery of the Th17 compartment, which is severely and permanently damaged during HIV-1 infection, might benefit from therapies including IL-21 treatment, manipulation of IDO1-mediated Trp metabolism, or microbiome-targeted interventions." (PMID 39842407, 2025). "The cellular immune system is activated during HIV-1 infection, which leads to the activation of IFN-γ-dependent pathways including neopterin production via GCHI and tryptophan catabolism via IDO1." (PMID 26236243, 2015). "It has already been reported that IDO1 expression in target cells suppresses HIV-2 infection, but not HIV-1 infection, and IDO1 inhibits the expression of HIV-1 proteins." (PMID 35883685, 2022). "Unlike the changes in IDO-1 expression, IDO-2 mRNA expression was not different between study groups, thus highlighting the pivotal immunosuppressive role of IDO-1 in HIV-1 infection." (PMID 24147117, 2013).
influenza (12 papers, 2013 to 2024). An acute viral infection of the respiratory tract, occurring in isolated cases, in epidemics, or in pandemics; it is caused by serologically different strains of viruses (influenzaviruses) designated A, B, and C, has a 3-day incubation period, and usually lasts for 3 to 10 days. "Thus, IDO was induced rapidly in response to local influenza infection, and IDO activity encoded exclusively by IDO1 genes continued to increase during infection and remained substantially higher than basal levels in lungs and msLNs long after sterile virus clearance occurred." (PMID 23785507, 2013). "Together, these data suggest an IDO1-independent role for IDO2 in the antibody response to influenza." (PMID 32973768, 2020). "To evaluate if IDO1 gene ablation affected host T cell responses to influenza infection we assessed virus-specific CD8 T cell responses in lungs and msLNs of B6 and IDO1-KO mice by flow cytometric analyses." (PMID 23785507, 2013). "Of the two homologous genes that encode IDO enzymes in mice, only the IDO1 gene encoded IDO activity induced by influenza infection, and intact IDO2 genes did not compensate for loss of IDO1 function in this setting." (PMID 23785507, 2013). "Moreover, recovery from influenza began earlier and progressed faster in IDO1-KO mice (open symbols)." (PMID 23785507, 2013). "Additionally, inhibiting IDO1 leads to increased T cell adaptive immune response to influenza infection, suggesting that controlling IDO1 activity during influenza vaccination may increase efficacy and robustness of the T cell response, improving influenza-specific heterosubtypic immunity." (PMID 39120289, 2024). "In preclinical models, pharmacological inhibitors of IDO1 have therapeutic utility in various diseases, including cancer, HIV and influenza." (PMID 36589459, 2022). "For example, the transcription level of indoleamine 2,3-dioxygenase 1 (IDO1), one metabolite of tryptophan, was significantly upregulated in response to influenza infection in mouse lungs and human primary macrophages." (PMID 35235615, 2022). "More influenza NP- and PA-specific BAL CD8+ T cells were present, and higher proportions of these cells expressed intracellular IFNγ and IL-10 in PR8-infected IDO1-KO mice." (PMID 23785507, 2013). "Prior to this study, antibody responses to influenza infection had not been evaluated in IDO1 ko mice, though T cell responses were shown to be elevated following infection." (PMID 32973768, 2020). "There exists a coincidence of peak IDO1 and IFN-k expression during influenza infection." (PMID 32161622, 2020). "Therefore, mice lacking IDO1 exhibit significantly lower morbidity after sub-lethal influenza A infection by generating a stronger influenza-specific effector CD8 T cell response, though viral clearance rates are unaffected by IDO1 ablation." (PMID 28066439, 2016). "To evaluate if influenza infection induced IDO in hematopoietic or non-hematopoietic cell compartments we lethally irradiated IDO1-KO mice and reconstituted them with bone marrow from B6 (WT) donor mice to generate B6→IDO1-KO chimeric mice." (PMID 23785507, 2013). "Moreover, numbers of CD8 T cells specific for NP366 and PA influenza epitopes were significantly higher in msLNs (∼2-fold) of IDO1-KO than B6 mice at 10 dpi, indicating that IDO activity restrains clonal expansion of CD8 effector T cells in msLNs." (PMID 23785507, 2013). "Thus more robust influenza-specific effector CD8+ T cell (CTL) responses manifested in mice lacking intact IDO1 genes, indicating that influenza-induced IDO activity attenuates clonal expansion and/or inhibits access of CTLs into infected lungs of IDO-sufficient mice." (PMID 23785507, 2013).
oral squamous cell carcinoma (12 papers, 2020 to 2025). "IDO1 expressing immune cells, especially macrophages, were found to be more abundant in malignant tissues and associated with worse prognosis of many cancer types, such as penile squamous cell carcinoma, oral squamous cell carcinoma of advanced stages, and classical Hodgkin lymphoma." (PMID 39351094, 2024). "In this study, we investigated the significance of IDO1 expressing immune cells in primary tumours and corresponding lymph node metastases (LNMs) in oral squamous cell carcinoma (OSCC) by immunohistochemistry." (PMID 35963900, 2023). "It has been observed that the increase in the expression of indoleamine 2-3-dioxygenase-1 (IDO1) reduces the proliferation not only of T-cells but also of other elements of the inflammatory infiltrate in oral squamous cell carcinoma." (PMID 36499710, 2022). "High IDO1 expression positively correlates with advanced stage in oral squamous cell carcinoma." (PMID 38736462, 2024). "Still, IDO1 is a useful marker for progression of in oral squamous cell carcinoma." (PMID 32117235, 2020). "AhR also plays a central role in IFNγ-induced expression of IDO1, PD-L1, CTLA-4, LAG-3, and CD39 in an oral squamous cell carcinoma model." (PMID 38632994, 2024).
preeclampsia (12 papers, 2014 to 2025). Preeclampsia is a hypertensive disorder of pregnancy that is characterized by new-onset hypertension with proteinuria presenting after 20 weeks of gestation, and depending on mild or severe forms may initially present with severe headache, visual disturbances, and hyperreflexia. "Reduced expression of IDO1 at the maternal–fetal interface has been associated with conditions, such as intrauterine growth restriction, preeclampsia, and recurrent miscarriage." (PMID 38831319, 2024). "Furthermore, IDO1 deficiency can lead to symptoms associated with preeclampsia, both in mice and humans, suggesting a resultant impairment in embryonic blood vessel development." (PMID 37182174, 2023). "IDO1 is the first enzyme of the kynurenine pathway of which we recently reviewed its placental functions and alterations in preeclampsia." (PMID 34992598, 2021). "The spatial distribution was not preserved in this study, therefore, it impossible to draw any further conclusions on the differential roles of IDO1 in preeclampsia." (PMID 34992598, 2021). "The decreased IDO1 expression in early-onset preeclampsia is in agreement with previous studies, and based on the current study, seems to be specific to early-onset preeclampsia." (PMID 34992598, 2021). "There are reports of reduced placental IDO1 mRNA, protein, and placental Trp-degrading activity in preeclampsia, including a correlation between reduced placental Trp-degrading activity and the severity of the disease." (PMID 24904580, 2014). "A similar preeclampsia-like phenotype was observed in IDO1-knockout mice." (PMID 34770059, 2021). "Interestingly, the expression of IDO1 was lower in the placentas of women with preeclampsia and correlated with disease severity." (PMID 34770059, 2021). "In a model of pregnant mice carrying hemiallogeneic concept, pharmacological inhibition of IDO1 was reported to result in the mothers developing high blood pressure, proteinuria, and impairment of the local placental circulation, analogous to the lesions characteristic of human preeclampsia." (PMID 24904580, 2014). "To summarize, placentas of women with preeclampsia display reduced IDO1 expression, but this does not affect its vasodilator function and the fetal tryptophan supply." (PMID 34770059, 2021). "In addition, disruption of the IDO1 gene induces IUGR and preeclampsia phenotypes in pregnant mice." (PMID 29615752, 2018). "However, IDO1 expression is reduced in FGR placentas, although one study reported a lower IDO1 expression in FGR and preeclampsia, but not FGR alone." (PMID 34770059, 2021).